IDO1 (indoleamine 2,3-dioxygenase 1)
Diseases named in the same sentence as IDO1 in open-access papers (continued):
Sharing a sentence is not in itself a finding about the gene and the disease.
acute myeloid leukemia (22 papers, 2011 to 2025). Acute myeloid leukemia (AML) is a group of neoplasms arising from precursor cells committed to the myeloid cell-line differentiation. "Analysis of the TCGA dataset showed a wide range of IDO-1 expression among different cancer types, with the highest median expression in diffuse large B-cell lymphoma and the lowest median expression in acute myeloid leukemia." (PMID 34367262, 2021). "A positive correlation was found between high IDO1 expression in bone marrow-derived mesenchymal stem cells and elevated percentage of Treg cells in acute myeloid leukemia." (PMID 28005163, 2017). "We aimed at determining whether COX-2 inhibitors down-regulate the IFN-γ-induced expression of IDO1 in acute myeloid leukaemia (AML) cells." (PMID 23973990, 2013). "Importantly, IDO1 confers an unfavourable prognosis to a variety of solid tumours and to acute myeloid leukaemia (AML)." (PMID 23973990, 2013). "Another study found that IFNγ secreted by acute myeloid leukemia (AML) cells upregulated IFNγ-dependent genes related to Treg induction, including IDO1, in mesenchymal stromal cells (MSCs)." (PMID 37876966, 2023). "Indoleamine 2,3-dioxygenase 1 (IDO1) is a tryptophan-catabolizing enzyme and is constitutively expressed by a variety of human cancers, including acute myeloid leukemia." (PMID 22567028, 2012). "Previous studies in childhood acute myeloid leukemia (AML) have shown a negative correlation of IDO-1 mRNA expression with outcomes." (PMID 29038460, 2017).
asthma (22 papers, 2011 to 2024). "In applications to ABRIDGE and CAMP cohorts, we find evidence of both differential co-expression and differential expression across ACT scores for ADORA3, ALOX15, and IDO1, all genes which have been previously implicated in asthma." (PMID 37275375, 2023). "Results suggest that both expression levels and covariances of ADORA3, ALOX15, and IDO1 are associated with asthma control." (PMID 37275375, 2023). "IDO1- deficient animals showed weaker Th2 responses in comparison to controls, when challengers with inhaled antigen and their serum levels of antigen-specific IgE were lower, indicating that IDO1-deficiency protected against ovalbumin-induced asthma." (PMID 34576041, 2021). "Although IDO1 protein expression is typically upregulated in asthma, the higher NO levels could cause a heme deficit that limits IDO1 heme content and Kyn production, thus diminishing immune suppression and enabling the lung inflammation that is a characteristic of severe asthma." (PMID 37116709, 2023). "It has been shown that asthma patients have low IDO-1 activity levels and high levels of tryptophan in lung tissue." (PMID 38378549, 2024). "Patients with asthma and AR had higher neopterin, tryptophan, and kynurenine levels, and lower IgE levels and IDO‐1 enzyme activity." (PMID 38342758, 2024). "Gut microbes are the major participants in tryptophan metabolism, which protects the host from developing asthma through indoleamine 2,3-dioxygenase-1 pathway and aryl hydrocarbon receptor activation." (PMID 34612663, 2021). "While, in another murine model of asthma using the same sensitization, induction of IDO1 expression inhibited Th2-induced asthma." (PMID 34576041, 2021). "The level of KYN/Trp is downregulated by OVA, indicating that asthma may decrease IDO-1 activity, altering the KYN pathway and further disrupting tryptophan metabolism by the gut microbiota." (PMID 38731707, 2024). "Indeed, IDO1 expressed in airways is reported to have lower-than-normal activity in both adult and pediatric patients with severe asthma, and in a mouse asthma model, active IDO1 protected the animals from developing severe airway inflammation." (PMID 37116709, 2023). "Enhanced formation of NO has been reported in patients with asthma and allergic rhinitis, and NO suppresses the activity of IDO-1, which may explain the higher levels of tryptophan in asthmatics." (PMID 33339279, 2020). "Also, the activity of indoleamine 2,3-dioxygenase-1 (IDO), an index of tryptophan breakdown, was decreased in airway of children with asthma." (PMID 32257919, 2019).
renal cell carcinoma (21 papers, 2015 to 2025). "Animal studies have shown that IFN-γ induced IDO1 restricted tumour growth and while clinical studies have shown that hepatocellular and renal cell carcinoma specimens evidenced a positive association between IDO1 expression and favourable outcomes." (PMID 26646699, 2016). "Renal cell carcinomas cells can increase tryptophan metabolism by upregulating indoleamine 2,3-dioxygenase 1 (IDO1), which results in T cell dysfunction and Tregs infiltration." (PMID 40122853, 2025). "Human primary gastric, colon and renal cell carcinomas were shown to constitutively express both IDO1 and IDO2 mRNA, whereas cancer cell lines generally required induction of IDO by interferon-gamma (IFNγ)." (PMID 26378585, 2015).
Cognitive impairment (20 papers, 2014 to 2025). Abnormal cognition is characterized by deficits in thinking, reasoning, or remembering. "We found that microglia reactivation accompanied by upregulation of IDO-1 mRNA and its neuroexcitatory metabolite QUIN in BLA was associated with postoperative cognitive impairment." (PMID 36160165, 2022). "They demonstrated that adjunctive antidepressant aripiprazole ameliorated depressive behavior and cognitive impairment in the ischemic mice via downregulation of IDO1, HAAO, QUIN, and ROS." (PMID 33192328, 2020). "The adjunctive antidepressant aripiprazole ameliorated depressive behavior and cognitive impairment in the PSD mice via downregulation of IDO1, HAAO, QUIN, and ROS." (PMID 30693061, 2018). "In order to confirm whether the KYN/TRP pathway was involved in drinking-induced emotional and cognitive impairments, IDO1 inhibitor 1-MT was administrated from the 4th to 8th week." (PMID 32116558, 2020). "The beneficial effect of aripiprazole on depressive-like behavior and cognitive impairment may be mediated by inhibition of IDO1, HAAO, QUIN, and ROS." (PMID 30693061, 2018). "IDO1 plays a crucial role in regulating immune responses and inflammation, potentially contributing to cognitive deterioration in PD patients, whereas MICB modulates natural killer and T cell activity, suggesting a complex immune regulatory mechanism underlying cognitive impairments." (PMID 40008429, 2025). "Systemic administration of IL-6 antibodies suppressed I/R-induced IL-6 elevations (P < 0.05), microglial reactivations (P < 0.05), IDO-1 expressions (P < 0.01), and neuroactive metabolite QUIN productions (P < 0.05) in the BLA, resulting in a recovery of cognitive deficits (P < 0.05)." (PMID 36160165, 2022).
lymph node metastasis (20 papers, 2006 to 2024). "In GC, IDO1 expression was significantly associated with the depth of tumor invasion and lymph node metastasis." (PMID 34943606, 2021). "IDO1 expression in the metastatic lymph node tumors was slightly but significantly (p < 0.001) higher than in the primary tumors." (PMID 38736462, 2024). "IDO1, which is overexpressed in NSCLC, is associated with higher pathological stages and lymph node metastasis, suggesting its role in immune resistance and tumor progression." (PMID 37816585, 2023). "IDO1 expression was related to advanced stage (p = 0.041) as well as lymph node metastasis (p = 0.033)." (PMID 38062922, 2023). "There is also evidence of immune system suppression in IDO1-positive advanced BrCa patients as IDO1 expressing breast tumours had higher numbers of infiltrating Tregs in tumour and lymph node metastases." (PMID 26646699, 2016). "Further, IDO1 positive breast tumours have a positive correlation with the density of immune suppressive Foxp3+ T regulatory cells and lymph node metastasis." (PMID 26646699, 2016). "We also found that the expression of the three LINC01871‐related mRNAs, namely, IDO1, CXCL10, and GBP4, was highly negatively correlated with TNM stage, lymph node metastasis, and liver metastasis." (PMID 38083905, 2023).
sarcoma (20 papers, 2016 to 2024). A usually aggressive malignant neoplasm of the soft tissue or bone. "A phase II trial with pembrolizumab plus IDO1 inhibitor epacadostat showed modest efficacy in 29 pre-treated advanced sarcomas (ORR 3%, DCR 48%)." (PMID 37190214, 2023). "Around 39% of human sarcoma express IDO1, especially when the CD8+ TILs infiltration is high, setting a rationale for the dual blockade of IDO1 and immune checkpoints." (PMID 37190214, 2023). "Given the known immune-suppressive role of IDO1 in sarcoma, explained above in detail, there is a rationale for combining ICIs with TKI against IDO1." (PMID 37190214, 2023). "In a phase II clinical study, it was found that most sarcoma cells were infiltrated by IDO1-expressing M2 macrophages, resulting in a low response to PD-(L) 1 inhibitor." (PMID 36110223, 2022). "IDO1 expression was observed in 39.1% of human sarcoma cases and was significantly higher in tumors with high CD8 infiltration." (PMID 32194552, 2020). "In fact, a high IDO1 expression may be used as a biomarker of poor response to anti-PD1 agents in sarcoma." (PMID 37190214, 2023). "Some studies have suggested that the IDO1 pathway could contribute to the immune-suppressive phenotype of sarcoma cells and be a relevant mechanism of their primary resistance to PD1 blockade." (PMID 37190214, 2023). "Strikingly, we found a statistically significant increase in the kynurenine/tryptophan ratio, a robust pharmacodynamic marker of the IDO1/Kynurenine pathway (KP), between pre-treatment and on-treatment plasma samples of sarcoma patients treated with Pembrolizumab." (PMID 32194552, 2020). "In sarcomas, IDO-1 targeting has been addressed in a publication where the IDO-1 expression was significantly correlated with high CD8+ infiltration, but no antitumoral activity was found with the combination of IDO inhibitor plus PD-L1 blockade." (PMID 34771683, 2021). "In order to investigate IDO1 expression in human STS, we performed an immunohistochemistry-based analysis for IDO1, PDL1, and CD8 markers of 203 cases of sarcomas with genomic complex." (PMID 32194552, 2020). "Before investigating the benefit of IDO inhibition in the preclinical sarcoma model, we evaluated the impact of GDC-0919—a novel IDO1 inhibitor—on Kynurenine and Tryptophan levels both at peripheral and tumoral levels." (PMID 32194552, 2020). "Using immunohistochemistry, IDO1 and CD8, expression profiles were addressed within 203 cases of human sarcomas." (PMID 32194552, 2020). "Treatment of sarcoma cells with HDAC inhibitors reduced the expression of PD-L1, PD-L2, ornithine decarboxylase (ODC), and indoleamine-pyrrole 2,3-dioxygenase (IDO-1), and increased expression of the class I MHC protein MHCA." (PMID 31380285, 2019). "In human sarcoma cells, exposure to axitinib and HDAC inhibitors rapidly increased the expression of MHCA and reduced the levels of PD-L1, PD-L2, ornithine decarboxylase (ODC) and indoleamine 2, 3-dioxygenase 1 (IDO1)." (PMID 34604061, 2021).
breast tumors (19 papers, 2011 to 2025). "Breast tumors presenting high expression of CD274 upregulated some ferroptosis drivers associated with prognosis: IDO1, IFNG and TNFAIP3." (PMID 38201582, 2023). "Quantitative real‐time PCR (qRT‐PCR) and WB results showed that compared to normal breast tissue, IDO1 protein, and mRNA levels in breast tumor tissue were significantly upregulated." (PMID 39661740, 2025). "TCGA bioinformatics analysis revealed that, compared to normal breast tissue (291 cases), IDO1 expression is significantly elevated in the breast tumors of BRCA patients (1085 cases)." (PMID 39661740, 2025). "The mRNA expression of IDO1 in breast tumor tissues was higher than that in normal and paracancerous tissues (p < 0.0001)." (PMID 39585774, 2025). "The upregulation of IDO1 in MDSCs causes an increase in the infiltration of CD4+CD25+FoxP3+ Tregs, and alters the immunosuppressive function in breast neoplasms." (PMID 39371092, 2024). "The expression of CD274, IFNG, TNFAIP3 and IDO1 was investigated in an independent cohort of the transcriptome: METABRIC cohort comprising 1866 breast tumors." (PMID 38201582, 2023). "In a murine breast tumor model, DCs loaded with tumor antigens and siRNA against IDO1 decreased the tumor size and the apoptosis of CD4+ and CD8+ T cells, when compared to DCs without IDO1 silencing." (PMID 30658461, 2019). "IDO1 mRNA levels were significantly increased in high AHR-expressing breast tumors relative to low AHR-expressing breast tumors in both ERα subpopulations." (PMID 29320557, 2018). "Two mouse breast tumor cell lines, 4T1 and NT-5, which showed differential expression of Ido1, were chosen." (PMID 22654951, 2012). "IDO1-positive breast tumors in immunocompetent mice show significantly higher levels of spontaneous lung metastasis compared to IDO1-negative tumors, while the opposite was observed in immunodeficient mice, confirming the immunosuppressive role of IDO1 in spontaneous metastasis formation." (PMID 39973065, 2025). "In breast tumors from the TCGA cohort, the expression of CD274 is associated with overall survival, and tumors presenting high expression levels of CD274 upregulated some ferroptosis-driver genes also associated with prognosis, like IDO1, IFNG and TNFAIP3." (PMID 38201582, 2023). "Hence, low SOCS3 expression is a probable factor in the enhanced IDO1 expression seen in TN breast tumors." (PMID 33109232, 2020). "Thus, the roles of Ido1 in breast tumor growth are complex and suggest the involvement of additional nonimmunological mechanisms." (PMID 22654951, 2012). "A strong correlation was therefore demonstrated between AHR, IDO1 and TDO2 expression in breast tumors." (PMID 29320557, 2018). "In addition to IDO1, PD-L1 (CD274) was also upregulated in placenta and breast tumor as compared to uterus and normal breast tissue." (PMID 27852037, 2016). "Our primary finding is that Ido1 expression has immunological and nonimmunological effects on breast tumor growth and spontaneous pulmonary metastasis formation." (PMID 22654951, 2012). "In the breast tumor transcriptome from the TCGA cohort, univariate overall survival analyses according to the expression of ferroptosis drivers highlighted a significant favorable expression for three of them: IFNG, IDO1 and TNFAIP3 conjointly with CD274 expression (univariate Cox p-value = 0.08)." (PMID 38201582, 2023). "Taken together, our findings indicate that Ido1 expression could exert immunological and nonimmunological effects in murine breast tumor cells." (PMID 22654951, 2012). "Interestingly, IDO1 levels, but not IDO2 levels (not expressed), were significantly elevated in high AHR-expressing breast tumors compared to low AHR-expressing breast tumors in both ERα subpopulations." (PMID 29320557, 2018).
esophageal cancer (19 papers, 2018 to 2024). A primary or metastatic malignant neoplasm involving the esophagus. "As for esophageal cancer, IDO1 was shown to be associated with immune tolerance and poor prognosis in patients with surgically resected tumours." (PMID 39351094, 2024). "Using mRNA gene expression of TCGA data, it was shown that increased IDO1 mRNA expression is associated with worse patient outcomes in esophageal cancer, both in SCC and AC histologies." (PMID 29805749, 2018). "In CRC and endometrial, ovarian, and esophageal carcinomas, the presence of IDO1 predicts poor clinical prognosis." (PMID 39371092, 2024). "In this manuscript, we investigate the role, expression pattern, and relevance of IDO1 in esophageal cancer via gene expression analysis of the cancer genome atlas (TCGA) and quantitative immunohistochemistry (IHC) of surgically resected esophageal tumors." (PMID 29805749, 2018). "Co-expression of mRNA for IDO1 and PD-L1 was found to be correlated with patient survival in esophageal cancer." (PMID 29805749, 2018). "This investigation began with an evaluation of the prognostic role of IDO1 as a predictor of patient survival in esophageal cancer." (PMID 29805749, 2018). "Interferon levels (IFNɣ and IFNβ) were correlated with IDO1 expression in the esophageal cancer patient samples from the TCGA (n = 198)." (PMID 29805749, 2018). "Additionally, several studies also showed that high IDO1 expression in tumor was correlated with worse overall survival (OS) in esophageal cancer." (PMID 32733806, 2020). "However, the role, expression pattern, and relevance of IDO1 in esophageal cancer (EC) are poorly understood." (PMID 29805749, 2018). "We hypothesize that the elevated IDO1 and PD-L1 expression in T-cell inflamed esophageal cancer lead to an immunosuppressive tumor microenvironment and contribute to worse OS." (PMID 29805749, 2018). "Recently, many studies have researched the IDO1 expression status of tumor cells and the density of CD8+ tumor-infiltrating lymphocytes (TILs) to predict the clinical outcome of esophageal cancer." (PMID 32733806, 2020). "Interestingly, the proteomic study on esophageal cancer also noted that the immune response genes that they identified as differentially expressed (MX1, IDO1, IFIT1, and IFIT3) did not correspond to alterations in published genomic data." (PMID 39285636, 2024).